DNMT3A (DNA methyltransferase 3 alpha)
Diseases named in the same sentence as DNMT3A in open-access papers (continued):
Sharing a sentence is not in itself a finding about the gene and the disease.
cancer (continued). "Although it seems that expressions of DNMT1, UHRF1, and DNMT3A are also upregulated in OXPHOS inhibition‐sensitive cancer cells identified in our screen, only DNMT1 expression exhibits a significantly positive correlation with cancer cell sensitivity to OXPHOS inhibition." (PMID 36382559, 2022). "However, in cancer cells, DNMT3A and DNMT3B enzymes synergistically enhance the DNMT1 activity and shift its activity towards de novo DNA methylation." (PMID 33498667, 2021). "In addition, it has been reported that DNMT3a can regulate the expression of apoptosis-related genes in cancer cells through changing the methylation levels at the promoter regions of the apoptosis-related genes, such as Bad, Bax and Bcl2." (PMID 33634123, 2021). "Depending on the cellular micro-environment H3K36me3 may help to established de novo DNA methylation via DNMT3A/B or decreased level of SETD2 can also be associated with increased DNA methylation at intergenic regions in disease condition such as, cancer." (PMID 34663428, 2021). "DNA methyltransferase 3A (DNMT3A) has been recognized as a promoting factor in various cancer." (PMID 34148029, 2021). "Remarkably, DNMT3A mutations, of which a considerable portion were filtered out as CH variants, generally occurred across all the cancer types but were absent in MSKCC." (PMID 33397889, 2021). "DNMT3A was found to be slightly overexpressed in other human cancers." (PMID 32751889, 2020). "In addition, DNMT3A has been reported to induce aberrant CpG site methylation in human cancer cells." (PMID 32363688, 2020). "Moreover, deletion of DNMT3a at an early stage of effector differentiation inhibited methylation of naive-associated genes and induced re-expression of these naive genes and the resultant memory cell development, which may induce potent anti-cancer responses in adoptive cell therapy." (PMID 32973749, 2020). "Cancer pathway, PI3K-Akt signaling pathway, and transcriptional misregulation in cancer may play a crucial role in DNMT3A mutation AML." (PMID 33299888, 2020). "However, more recently direct miRNA targeting of DNMT3a/b has shown the potential for both oncogenic and tumour suppressor activities in the progression of cancer such as breast cancer." (PMID 33050637, 2020). "In addition, miR-30b has been shown to regulate DNA methyl transferase 3 alpha (DNMT3A) expression that can be used as a potential biomarker and a therapeutic target for cancer." (PMID 31954402, 2020). "KEGG pathway enrichment analysis indicated that the pathway of cancer, PI3K-Akt signaling pathway, and transcriptional misregulation in cancer may play a crucial role in DNMT3A mutation AML." (PMID 33299888, 2020). "Moreover, a different line of evidence revealed that UHRF1 overexpression also acts as a negative regulator by degradation of the de novo DNA methylation protein, DNMT3A, as an additional mechanism leading to widespread DNA hypomethylation in cancer cells." (PMID 31249594, 2019). "H3K36me3 is also involved in targeting DNMT3A to chromatin, highlighting the finely tuned epigenetic interplay between histone and DNA methylation that is needed for normal cell function and is frequently disrupted in cancer cells." (PMID 30897760, 2019). "The DNMT1 was significantly associated with patient survival times only in one cancer type (not shown), and it was seen that the DNMT3A expression did not affect patient survival." (PMID 31828117, 2019). "The levels of DNMT3B and DNMT3A are often increased in various cancer tissues and cell lines." (PMID 30405408, 2018). "De novo DNA methylation activity, catalyzed by DNMT3A and DNMT3B, is essential during embryonic development or gametogenesis but is also frequently associated to aberrant gene repression in many pathologies (e.g., cancer)." (PMID 29449903, 2018).
cancer (continued). "Most importantly, increased DNMT3A expression is closely linked to the poor survival rate of GC patients but not for patients with other cancers, including breast cancer, lung cancer and liver cancer (analysis from the Kaplan–Meier plotter website)." (PMID 29717263, 2018). "In addition to having a methyl-transferase activity, DNMT3B also acts as an accessory protein in complex with DNMT3A contributing to aberrant methylation in cancer." (PMID 29928480, 2018). "Here we investigated the role of MTA1 in the regulation of DNMT3a expression in cancer cells." (PMID 28393842, 2017). "Apart from being involved in the cancer progression, low levels of DNMT3a could result in an unscheduled activation of EPAS1 gene which contributes to cell survival under extreme hypoxic conditions." (PMID 28393842, 2017). "Thus, both UHRF1 and UHRF2 negatively regulate de novo DNA methylation by targeting DNMT3A degradation in both normal somatic and cancer cells." (PMID 27462454, 2016). "Furthermore, our studies with cancer cell lines demonstrated that UHRF1/2 actively downregulates DNMT3A in all cancer cell lines tested." (PMID 27462454, 2016). "To test if UHRF1/2 overexpression indeed leads to downregulation of DNMT3A proteins in cancers despite DNMT3A overexpression at the level of transcription, we next examined the levels of UHRF1, UHRF2 and DNMT3A proteins in paired lung tumors and adjacent normal controls by western blot analysis." (PMID 27462454, 2016). "We next wished to test whether negative regulation of DNMT3A by UHRF1/2 contributes to DNA hypomethylation in cancer." (PMID 27462454, 2016). "The substantial increase in LINE1 methylation in shUHRF2-expressing A549 cells is consistent with the notion that DNA hypomethylation in cancer occurs primarily in repetitive sequences and that DNMT3A plays a critical role in maintaining DNA methylation in repetitive sequences." (PMID 27462454, 2016). "As UHRF1 is also required for DNA maintenance methylation, we could not manipulate the level of UHRF1 in cancer cell lines to test whether negative regulation of DNMT3A by UHRF1 contributes to DNA hypomethylation in cancer." (PMID 27462454, 2016). "Though our insights are from ES cells, we expect that cancer stem cells or somatic cancer cells would have similar behaviors because the overexpression of de novo methyltransferase DNMT3a and/or 3b in different types of cancer has been reported in numerous studies." (PMID 26032981, 2015). "Our discovery that higher PADI4 levels lead to increased DNMT3A expression and stability might explain, at least partially, the observed hypermethylation of some promoters in cancers." (PMID 24957603, 2014). "Characterizing larger DNMT3A-induced changes in the cancer methylome has proven quite challenging." (PMID 24622842, 2014). "One study with prostate cancers demonstrated that the activity of DNMT1, DNMT3a, and DNMT3b are twofold to threefold higher in cancer cell lines and cancer tissues, as compared with a benign prostate epithelium cell line and benign prostatic hyperplasia tissues." (PMID 24822169, 2014). "The importance of the DNMT3A gene in the regulation of DNA methylation and gene expression makes it attractive for further study of other cancers and it could be a useful marker for epidemiological study." (PMID 20128888, 2010). "A direct link between LANA and the de novo methyltransferase DNMT3a has been proposed in a study, that reveals that LANA recruits DNMT3a to the chromatin and targets repression of approximately 80 cellular genes, some of which are known targets of epigenetic inactivation in various cancers." (PMID 17179991, 2007).
cancer (continued). "Taken together, DNMT3A demonstrates multi-layered evidence—ranging from early overexpression in diseased liver to diagnostic accuracy in HCV-related cohorts, and from correlation with recurrence and survival to functional ties with cancer stemness—making it an actionable epigenetic biomarker in HCC." (PMID 41465346, 2025). "On the other hand, our analysis also showed hypomethylated DMPs for some genes, confirming previous reports showing that upregulated UHRF1/2 could mediate DNMT3A ubiquitination and proteasome-dependent degradation, leading to genome-wide de novo DNA methylation in cancer cells." (PMID 34294135, 2021). "Interestingly, our panel included genes already described to be cancer predisposition genes (FAS, ITK, KIF1B, PGR and MET) or previously reported as playing important roles in cancer (ABI1, ARID5B, DNMT3A, HEY1, KDM5C, NCOA1, NUP98, and SLC34A2), or in DNA repair process (FANCF)." (PMID 30925779, 2019). "Indeed, analysis of Cancer Cell Line Encyclopedia confirmed that Ets1 expression was negatively correlated with Dnmt3a (Spearman r = −0.4139, **p = 0.0011) and Dnmt3b (Spearman r = −0.5878, ***p < 0.0001) but positively with Apobec3c (Spearman r = 0.6239, ***p < 0.0001)." (PMID 30467308, 2018). "However, the role of Dnmt3a and Dnmt3b in many types of cancer remains undefined." (PMID 28425913, 2017). "However, it should be noted that it is DNMT3B, but not DNMT1 or DNMT3A, that has been implicated in aberrant DNA methylation in tumorigenesis for several types of cancer." (PMID 28160561, 2017). "Since aberrant DNA methyltransferases (Dnmts) activity has been reported in numerous cancers, we examined the expression of the 3 major Dnmts: Dnmt1, Dnmt3a and Dnmt3b which are known to be involved in DNA methylation maintenance (Dnmt1) or de novo methylation (Dnmt3a and Dnmt3b)." (PMID 29073177, 2017). "The widespread UHRF1/2 overexpression in cancers shown in this and previous studies provides an alternative and possibly more prevalent mechanism for inactivating or suppressing DNMT3A activity in cancers, which may in turn promote tumorigenesis through consequent DNA hypomethylation." (PMID 27462454, 2016). "The observed resistance to demethylation at these loci could be explained by redundant activities in the establishment and maintenance of DNA methylation by DNMT3A and DNMT1, respectively, being capable of activity compensating for the loss of DNMT3B in human cancer cells in vitro." (PMID 22563479, 2012). "Therefore, any inhibitory interaction between any of the screened dietary polyphenols and Dnmt3a might allow identification of compounds that have a positive effect on cancer prevention and improved mental performance." (PMID 21510884, 2011). "In the process of cancer development, various DNMTs (DNMT1, DNMT3A, and DNMT3B) and HDACs (HDAC 1, 2, 3, and 6) are reported to be overexpressed in different cancers." (PMID 41562705, 2026). "Specifically, STAT3 phosphorylation has been found to increase DNMT1, DNMT3A, and DNMT3B expression in cancer cells." (PMID 40427627, 2025). "These radiation-induced methylation patterns not only affect cancer treatment outcomes through DNMT1, DNMT3A/B, and DNMTis-related mechanisms but also contribute to long-term normal-tissue effects such as radiation-induced cardiovascular disease." (PMID 41369374, 2025). "Upon treatment of the different cancer cell lines (HaCaT, HepG2, and A549 cells) with TRZ in our study, DNMT1, DNMT3a, and DNMT3b were significantly upregulated at concentrations of 20, 40, and 80 μM for a duration of 24 h." (PMID 40077783, 2025).
cancer (continued). "The data presented uncovers a functional role of the DNA demethylation activity of DNMT3A in vivo, which appears to link the HIF pathway and O2-sensing KDM pathway for the regulation of hypoxia-induced EMT of cancer cells." (PMID 40764968, 2025). "In laboratory settings, DNC has been shown to reactivate the expression of miR-34s by inhibiting DNMT1, DNMT3A, and DNMT3B in HepG2 and Huh7 cell lines, reducing the viability of these cancer cells." (PMID 39829957, 2025). "The results indicated that USP37 was significantly associated with at least one of the four methyltransferase genes (DNMT1, DNMT2, DNMT3A, and DNMT3B) in various cancer types, except UCS." (PMID 40926837, 2025). "DNA methyltransferases, such as DNMT3A, silence STING in cancer and chronic infections, a feature reversed only under acute stress or demethylation therapies." (PMID 40607404, 2025). "Similar to the NSCLC validation cohort, patients with TET2-mutant CHIP from the pan-cancer cohort had the highest frequency of TI-CH (33%, 381/1191), followed by ASXL1-mutant (32%, 124/392), DNMT3A-mutant (25%, 926/3,753), and PPM1D-mutant CHIP (13%, 83/622)." (PMID 40267425, 2025). "DNMT3a expression was the highest in VLSIL (VIN I) samples, while DNMT1 was only expressed in VHSIL (VIN III) and carcinoma samples." (PMID 40022051, 2025). "DNMT1 and DNMT2 are positively correlated with most cancers, while DNMT3A and DNMT3B are inversely correlated with most cancers." (PMID 38166842, 2024). "Although the oncogenic mechanisms of DNMT3A and TET2 should be further explored, they have a wide range of applications as potential therapeutic targets for cancer." (PMID 38246976, 2024). "The present study has identified 4 cancer driver genes (PTCH1, DNMT3A, PTPRS, JAK2) that rank highest in responders and are linked to enhanced survival in the validation cohort, either as individual markers or as part of a grouped marker panel." (PMID 38951894, 2024). "For DNA methylation regulatory factors, the specific functions and molecular mechanisms of DNMT1, DNMT3A, DNMT3B, and TET family proteins have been extensively studied in various malignant tumors." (PMID 38308276, 2024). "EZH2 was also shown to interact with DNMT1, DNMT3A, and DNMT3B in cancer cells and to result in the hypermethylation of genes, leading to increased permanent silencing of target genes." (PMID 39409007, 2024). "However, in Japan, expert panels frequently discuss the possibility that ASXL1 and DNMT3A alterations may represent clonal hematopoiesis rather than somatic mutations caused by cancer." (PMID 39597083, 2024). "The relationship between the expression of four methyltransferase genes (DNMT1, (DNMT2, DNMT3A, DNMT3B) and SNAI2 in pan-cancer was investigated further." (PMID 37251370, 2023). "miR-770-5p binds to 3’-UTR of DNMT3A mRNA and down-regulates DNMT3A, thereby reducing promoter methylation of CDH1 and increasing its expression, thus playing a role in cancer inhibition." (PMID 37901333, 2023). "Aberrant methylation often results in cancer development through the many-fold expression of DNA methyltransferases (DNMT1, DNMT3a, and DNMT3b) that is comparatively significantly higher than their normal expression in healthy cells." (PMID 36765652, 2023). "Overexpression of LinC00472 can recruit DNMT1, DNMT3A and DNMT3B to mediate the methylation of oncogenic factor MCM6, which leads to the down-regulation of its expression level, and then inhibits cancer progression by inactivating MEK/ERK signaling pathway." (PMID 37901333, 2023). "Further studies showed that overexpression of miR‐29b‐1‐5p inhibited DNMTs (DNMT1, DNMT3A, and DNMT3B) and promoted the expression of some cancer suppressor factors." (PMID 37901333, 2023). "Significant correlations of BCAT1 expression with the three methyltransferases—DNMT1, DNMT3A, and DNMT3B—were detected in some cancers." (PMID 34984849, 2022).
cancer (continued). "We noted that EVA1B presented negative interactions with four major DNA methyltransferases containing DNMT1, DNMT2, DNMT3A, and DNMT3B in most cancer types." (PMID 35250982, 2022). "Knockdown of MLL4 leads to a marked decrease in DNMT3A and DNMT1 levels in several human cancer lines we examined." (PMID 36323669, 2022). "In our research, BCAT1 expression was correlated with the three DNA methyltransferase genes––DNMT1, DNMT3A, and DNMT3B in some cancers." (PMID 34984849, 2022). "At the same time, in an in vitro study of curcumin in several human cancer cell lines, curcumin induced some global DNA hypomethylation and altered the expression of three DNMTs: DNMT1, DNMT3A, and DNMT3B." (PMID 36499286, 2022). "In this review, we mainly summarize the roles of DNMT1, DNMT3A, and DNMT3B in cancer, hoping to shed new light on the treatment of cancer." (PMID 36091786, 2022). "Aberrant DNA methylation has been established as key molecular events contributing to tumorigenesis, and targeting DNMT1, DNMT3A, and DNMT3B with 5-azacytidine (Aza) and 5-Aza-2’-deoxycytidine were suggested as promising strategies for cancer treatment." (PMID 33589600, 2021). "In epithelial cancers, LMP1 indeed mediates the expression of host genes via DNA methylation through up-regulation of DNMT1, DNMT3A and DNMT3B, which further promotes the migration of cancer cells." (PMID 34946098, 2021). "DNA methylation is an important epigenetic mechanism regulating gene expressions through three DNA methyltransferases (DNMT1, DNMT3A, and DNMT3B) and affects cancer cell behaviors." (PMID 33612479, 2021). "DNA hyper-methylation at NF2 and KIBRA promoter mediated by MOC2 and DNMT3a complexes suppresses their gene expression and Hippo signaling pathway activation, which further promotes HCC cancer stemness and tumorigenesis." (PMID 33234142, 2020). "Among epigenetic genes, DNA methylation related epigenetic modifiers, DNMT1, DNMT3A, MBD1, MBD4, TET1, TET2, and TET3, have been studied related to cancer." (PMID 32093698, 2020). "In our study, we also found that NFE2L2 expression was closely correlated with that of 4 DNA methyltransferases (DNMT1, DNMT2, DNMT3A, and DNMT3B) in human cancers, especially in COAD, KIRP, LGG, and UVM." (PMID 33101586, 2020). "In this paper, we investigated the effect of mutations on DNA methylation modification genes such as DNMT1, DNMT3A, MBD1, MBD4, TET1, TET2, and TET3 through a pan-cancer analysis." (PMID 32093698, 2020). "Evidently, NFE2L2 expression is closely related to the expression of DNMT1, DNMT2, DNMT3A, and DNMT3B across human cancers, especially in COAD, KIRP, LGG, and UVM." (PMID 33101586, 2020). "This category also includes many known biomarkers for cancer diagnosis or targeted treatment, such as APC Q1291* (for COAD), EGFR L858R (for LUAD), BRAF V600E (for THCA and SKCM), DNMT3A R882H and NPM1 W288Cfs*12 (for LAML)." (PMID 31925297, 2020). "Only DNA methyltransferase (DNMT) genes were presented in results: DNMT1, DNMT3A, and DNMT3B were all highly expressed in 8, 6, and 9 cancer samples compared with normal, respectively." (PMID 31828117, 2019). "To better understand the relevance of de novo DNMT expression in cancer biology, we began by exploring the mechanism and frequency of DNMT3A and DNMT3B deregulation across different human cancer types." (PMID 30468428, 2018). "Whereas DNMT3A and DNMT3B are the de novo methylation enzymes, and their importance is correlated with the embryogenesis and pathogenesis of cancer cell." (PMID 30405408, 2018). "To understand the physiological relevance of MTA1 stimulation of IGFBP3 expression in cancer, we examined the status of MTA1 and IGFBP3 in context of DNMT3a expression in human tumors." (PMID 28393842, 2017). "To test potential DNMT involvement in VEGFA‐driven miR‐128‐2 repression, and since DNA methyltransferases genes, DNMT3A, DNMT3B, DNMT1, are often coregulated and elevated in cancer stem‐like cells, we assayed all three methyltransferases." (PMID 28179359, 2017).